IL10 (interleukin 10)
Diseases named in the same sentence as IL10 in open-access papers (continued):
Sharing a sentence is not in itself a finding about the gene and the disease.
tumor (continued). "Studies have reported that a lack of IL-10 may stimulate the secretion of pro-inflammatory cytokines that inhibit anti-tumor immune responses and enhance growth of tumor." (PMID 37684564, 2023). "However, their tumor-killing ability is counteracted by various factors, such as indoleamine 2,3-dioxygenase (IDO), vascular endothelial growth factor (VEGF), interleukin 10 (IL-10), hypoxia, and CD4+ T-cell deprivation." (PMID 37275909, 2023). "Similarly, the expansion of IL-10+ CD1d+ CD5+ CD138+ CD19+ Bregs within TNBC may enhance the differentiation of anti-inflammatory M2 macrophages and Tregs to tone down anti-tumour responses." (PMID 36900307, 2023). "Additionally, the hypoxic, glucose, and amino-acid-deprived tumor microenvironment (TME) of AML produces metabolites such as adenosine and suppressive cytokines such as IL10, IL6, and TGF-β, which all contribute to unfavorable metabolism and the suppression of CAR-NK cell activity." (PMID 37297016, 2023). "Furthermore, through the secretion of adrenomedullin and vascular epithelial growth factors (VEGFs), and the expression of several immunosuppressive molecules (such as IL-10, programmed death-ligand 1 (PD-L1), or TGF-β, promoting tumor growth), M2 macrophages support angiogenesis in cancer cells." (PMID 37958467, 2023). "Furthermore, fruquintinib can correct the immune escape microenvironment of tumor cells, mainly by inhibiting PD-L1 expression, inhibiting tumor release of inflammatory factors and immunosuppressive factors such as IL6/IL-10/VEGFR, and inhibiting bone marrow-derived suppressor cells." (PMID 36969012, 2023). "We found that conditional deletion of IL-10 within T cells resulted in loss of resistance to Treg cell depletion, as indicated by reduced tumor growth when Treg cells were ablated in animals lacking T cell-restricted IL-10 expression, but not when either condition was present alone." (PMID 38100544, 2023). "At the same time, the upregulation of PD-L1 on dendritic cells inhibits the secretion of IL-2, IL-10, INF-γ, INF-α and other cytokines by T lymphocytes in the tumor microenvironment, downregulates the immune “surveillance” function of T cells, and mediates tumor immune escape." (PMID 37006252, 2023). "These subsets may be Bregs expressing or secreting inhibitory factors such as IL-10 to establish an immune environment promoting tumor metastasis or other B-cell subsets that have not been clearly classified that promote tumor metastasis." (PMID 37215990, 2023). "IL-10 may decrease the production of proinflammatory cytokines such as IL-6, TNF-α, and IFN-γ and thus promote polarization of macrophages toward the protumorigenic M2 phenotype and thus ultimately enable tumor cells to evade immune surveillance." (PMID 38033495, 2023). "We found that PPARδ is significantly upregulated in tumor-induced IL-10+ Bregs with a phenotype of CD19+CD24hiIgDlo/−CD38lo or CD19+CD24hiIgDlo/−CD38hi in both mice and humans, and the level of PPARδ expression was correlated with their potential to produce IL-10 and to inhibit T cell activation." (PMID 37291146, 2023). "Additionally, tumor-derived EVs containing lnc-TALC can promote the M2 polarization of microglia by increasing the expression of Arginine-1 (Arg-1) and CD163, as well as M2-related cytokines (TGF-β, IL-4 and IL-10), via p38 of the MAPK pathway activation." (PMID 37175226, 2023). "Interestingly, we demonstrated that DHEA educated TAMs in a less aggressive phenotype, reducing the gene expression of several markers of TAM phenotype, including IL-6, MMP-9, VEGF, IL-10, and MPC-1, which sustain tumor invasiveness, angiogenesis, and metastasis." (PMID 36765778, 2023). "If IL-10 acts like a tumor suppressor in CLL, why does ibrutinib not also activate CLL cells?" (PMID 37114129, 2023).
tumor (continued). "In the case of solid tumors, such as HCC, VEGF is secreted by hypoxic tumor cells and vascular endothelial cells, and leads to the recruitment of regulatory T cells, TAMs, and MDSCs, which in turn release additional VEGF and immunosuppressive cytokines (e.g., IL-10, TGF-β)." (PMID 38069095, 2023). "Finally, cytokines measurement showed, in tumor mass of αPD-L1-treated mice, an increased level of cytokines known to exert anti-tumoral actions such as TNF-α, IFN-γ, and IL-6, and a concomitant decrease of the immune-suppressive cytokine IL-10." (PMID 36854895, 2023). "For example, the reduction of IL-10 concentration in TME achieved by intratumoral injections of lentiviral vectors carrying the shRNA sequence directed against IL-10 significantly improved the effectiveness of DC-based vaccines and contributed to the inhibition of the MC38 tumor growth." (PMID 37033926, 2023). "Moreover, antigen-specific induction of tumor-specific T cell responses and tumor suppression was achieved, supported by the elevated levels of IFN-ɣ-expressing CD8+ T cell and decreased levels of immunosuppressive cytokines such as IL-10 and TGF-β." (PMID 37681880, 2023). "Tumor-specific TCRα and TCRβ sequencing demonstrated that the CD8+ cells from tumors or tdLNs of BF10-treated mice harbored the highest clonotype diversity compared with the other groups, whereas IL-10-Fc treatment increased the diversity of the TCR repertoire of CD8+ cells from spleen." (PMID 37586318, 2023). "Another form of half-life-extended IL-10 includes an immunoglobulin Fc domain fusion protein (IL-10-Fc), which acts directly on CD8+ terminally exhausted T cells to reprogram metabolic activities, restoring their proliferation and antitumor activity in mouse tumor models." (PMID 37586318, 2023). "Moreover, IL-10 and TGF-β are known as immunosuppressive mediators and tumor promoters." (PMID 36814925, 2023). "On the contrary, M2 macrophages release cytokines such as IL-10, IL-13, CCL9 and transforming growth factors to destroy the basement membrane, promoting angiogenesis and recruiting immunosuppressive cells to facilitate the development of primary tumor and metastasis." (PMID 37907987, 2023). "Meanwhile, we analyzed the cytokines in the tumor by ELISA, and the analysis showed that the combination therapy significantly increased the immunostimulatory cytokines (TNF‐α, IFN‐γ, and IL‐12) and decreased the immunosuppressive cytokines (IL‐10 and TGF‐β) compared with the monotherapy." (PMID 37552209, 2023). "In this study, we report that PPARδ is highly expressed in IL-10+ Bregs with a predominant surface phenotype of CD19+CD24hiIgDlo/−CD38lo or CD19+CD24hiIgDlo/−CD38hi, which present in naïve mice and can be induced by tumor formation and agonistic anti-CD40 mAb." (PMID 37291146, 2023). "TGF-β in tumour microenvironment may limit the synthesis of pro-inflammatory immune factors such as TNF-α, IFN-γ and IL-12, while promoting the release of anti-inflammatory factors such as IL-10." (PMID 37162544, 2023). "In addition, this study also demonstrated that low expression of SHP-2 further stimulated IL-4-induced M2 macrophages to produce IL-10 and Arginase-1, which in turn further aggravated macrophage M2 polarization and ultimately promoted CRC tumor invasion and metastasis." (PMID 36776333, 2023). "In addition, compared with the model group, 20 mg/kg of erianin could dramatically restrain the tumor growth of tumor-bearing mice, and significantly reduced the level of MMP-2, -9, and IL-10 in the serum." (PMID 37608888, 2023). "Meanwhile, several potent immunosuppressive factors produced by M2 macrophages (such as IL-10 and prostaglandin E2 [PGE2]) suppress anti-tumor immune responses and promote angiogenesis and stromal remodeling in the tumor microenvironment, ultimately promoting tumor development and metastasis." (PMID 37153586, 2023).
tumor (continued). "Furthermore, functioning as immunosuppressive cells, TAMs produce a variety of immunoregulatory cytokines such as TGFβ, IL-10, and prostaglandin E2 (PGE2) and express inhibitory molecules PD-L1 and PD-L2, which promote Treg cell infiltration and inhibit anti-tumor CD8 T cell activity." (PMID 37771596, 2023). "Conversely, other studies have suggested that IL-10 can enhance the proliferation and activation of CD8+ T cells while suppressing the expression of IFN-g-induced cytokines and specific pro-inflammatory cytokines (IL-12 and IL-6), leading to an anti-tumor effect." (PMID 37910571, 2023). "However, the tumor microenvironment became immunosuppressive upon CART cell injection, with the expression of many immunosuppressive molecules, particularly IDO1, FoxP3, IL-10, PD-L1, and/or TGFβ." (PMID 37274252, 2023). "Additionally, tumor cell metabolism can shape the composition and functionality of immune cell populations by releasing factors such as transforming growth factor-beta (TGF-β) and interleukin-10 (IL-10), which suppress immune responses." (PMID 38075052, 2023). "However, there was no meaningful difference between the tumor and normal samples for IL-10, and IL-12β (p > 0.05)." (PMID 38075864, 2023). "It was shown that in ovarian cancer, miR-217 inhibits tumour-induced M2 macrophage polarisation by targeting IL-6 and regulating the JAK3/STAT3 signalling pathway and that in renal cell carcinoma, BMP-6 induces M2 polarisation through activation of the Smad5/STAT3 pathway by IL-10." (PMID 38143746, 2023). "The tumor vasculature primarily comprises endothelial cells, playing a critical role in tumor growth and facilitating immune reactions within the TME through the release of various neuroimmune substances, including IL-1β, IL-10, and granulocyte-macrophage colony-stimulating factor (GM-CSF)." (PMID 37533851, 2023). "Finally, we also found that FH-deficient tumour tissue exhibited increased levels of interleukin-6 (IL-6), but not IL-10, confirming the presence of an inflammatory milieu in these tumour tissues." (PMID 36890229, 2023). "Moreover, another study showed that tumor-derived exosomes induce GPX3 expression in a subpopulation of alveolar type 2 epithelial cells, inducing high production of IL-10 and ultimately improving Treg cells generation and inhibiting the proliferation of T helper cells." (PMID 37915578, 2023). "Moreover, SCF enhances tumor growth through and increased release of VEGF, IL-10, and TNF-α." (PMID 37038035, 2023). "Similarly, IL-10, an anti-inflammatory cytokine, can also drive TAMs towards the M2 phenotype, resulting in macrophages that are generally immunosuppressive and produce factors such as VEGF and EGF, which promote tumor growth and angiogenesis." (PMID 37895855, 2023). "In addition, the increase in CD86/CD206, TNF-α/IL-10, and CD8/FoxP3 ratios of TAM after administration also suggested that this regime could modulate the tumor microenvironment toward a pro-inflammatory phenotype." (PMID 37598273, 2023). "When the cutoff level of the WT1-332-specific IL-10 IR index was set as 1.15, the group with a higher WT1-332-specific IL-10 released from PBMCs had a significantly lower completion rate and a higher rate of tumor progression than the group with lower WT1-332-specific IL-10 released from PBMCs." (PMID 36672344, 2023). "Notably, WCP could inhibit the proliferation of H22 tumors not only by improving immune function, but also by promoting the apoptosis of tumor cells, likely through the IL-10/STAT3/Bcl2 and Cyto-c/Caspase8/3 signaling pathways, in H22 tumor-bearing mice." (PMID 37110586, 2023). "Since our results demonstrated that IL-10 and IL-6 cytokines levels are crucial in defining the antitumoral action of mifamurtide, we first assayed cell viability of OS tumor cells treated with mifamurtide in the presence or absence of anti-IL-10 and anti-IL-6 blocking antibodies." (PMID 37835437, 2023).
tumor (continued). "Th1 cells suppress malignant tumor proliferation via inducing an immune response to tumors by mainly secreting interferon‐γ (IFN‐γ) and tumor necrosis factor‐α (TNF‐α); while Th2 cells mainly secrete interleukin‐4 (IL4), IL‐10 leading to tumor immunosuppression." (PMID 37096492, 2023). "Interestingly, it was observed that the vascular endothelial cells of some solid tumors also express the membrane-bound form of CD95L through a mechanism involving tumor-derived vascular endothelial growth factor A (VEGF-A), interleukin 10 (IL-10) and prostaglandin E2 (PGE2)." (PMID 35301281, 2022). "Systemic application of type I IFNs in tumor therapy to enhance CD8 T-cell responses is, however, only resulting in short-term anti-tumor action because of negative effects during prolonged IFN signaling by inducing immunosuppressive factors such as PD-L1 and IL-10." (PMID 36118237, 2022). "In response to inflammatory stimuli, such as tumor growth, brain stromal cells produce high levels of classic immunosuppressive cytokines such as transforming growth factor beta (TGF-β) and interleukin-10 (IL-10), which counteract the inflammatory cytokine signals to maintain homeostasis." (PMID 34825292, 2022). "Tregs drawn by the tumor have higher suppressive properties compared to circulating Tregs and are able to inhibit the anti-tumor activity of other immune cells directly using cell–cell interactions or indirectly through synthesis and the secretion of mediators, e.g., TGF-β, interleukin 10 (IL-10)." (PMID 36139368, 2022). "Interleukin-10 (IL-10) and transforming growth factor (TGF) are two immunosuppressive substances that tumors may explicitly or implicitly release, helping to create an immunosuppressive microenvironment inside and surrounding the tumor." (PMID 36016257, 2022). "However, Tumor cells evade immunity through the expression of programmed cell death ligand (pdl-1) and similar inhibitory gene products, such as indoleamine 2 and 3 dioxygenase (Ido), transforming growth factor-β (TGF-β) and interleukin-10 (IL-10)." (PMID 36032103, 2022). "The release of inflammatory factors, including IL-1β, IL-1 receptor antagonist, IL-8, IL-10, and tumor necrosis factor-alpha (TNF-α) changes the adhesion of gastric mucosal cells, which leads to the migration and diffusion of tumor cells without mutations of tumor suppressor genes." (PMID 36185234, 2022). "For tumor cells, STAT3 decreases the production of immuno-stimulatory cytokines such as interferon-γ (IFN-γ) and tumor necrosis factor-α (TNF-α), along with elevated expression of immuno-exhausting cytokines (IL-6, IL-10, transforming growth factor-β [TGF-β], and VEGF)." (PMID 36080223, 2022). "As the tumor progresses, cancer cells shape the tumor infiltrate profile by secreting chemotactic factors such as CCL2 (which recruits myeloid cells), and cytokines like TGF-β and IL-10 (which promote an immunosuppressive milieu), favoring the continued growth of the tumor." (PMID 35472214, 2022). "In addition, IL-10 and prostaglandin E2, which are immunosuppressive factors, are produced and promote Fas ligand expression along with VEGF, thereby inducing apoptosis of CD8+ T cells infiltrating the tumor." (PMID 35685630, 2022). "Furthermore, IL-4 and IL-10 restrain IFN-γ production and impair cytotoxic cell-mediated anti-tumor immunity, suggesting that an increased shift from Th1 cells to Th2 cells promotes tumor progression and immunosuppression." (PMID 35646684, 2022). "Additionally, some cytokines and chemokines may also participate in this process, since M2 TAMs also secrete IL-8, IL-10, TGF-β, CCL2, CCL4, CXCL13, and other soluble mediators that are capable of inducing tumor growth in vitro and in vivo." (PMID 36532078, 2022). "Moreover, IL-10 blockade enhanced the effect of the co-administration by eliciting higher levels of IFN-γ and caspase-9, reducing Il-10 secretion and provoking the regression of tumor size." (PMID 35752792, 2022).
tumor (continued). "However, the tumor suppressor lncRNA FENDRR targets GADD45B as a miR-423-5p sponge to suppress the secretion of immune-related factors TGF-β, vascular endothelial growth factor (VEGF), IL-2, and IL-10, thereby suppressing Treg-mediated immune escape." (PMID 36300115, 2022). "IL-10+ IgA-producing B cells could be categorized as a part of Breg cells, which suppress the anti-tumor immunity, other Breg cells such as TGF-β-producing B cells or IL-21-producing B cells also limit anti-tumor immunity." (PMID 36033455, 2022). "As macrophages enter solid tumors, cytokines such as IL-10 and TGF-β released by tumor cells may promote the development of immunosuppressive TAMs, which promote tumor growth and metastasis, and suppress the anti-tumor activity of infiltrating T cells." (PMID 35884798, 2022). "In addition, mast cells support tumor invasiveness by their immunosuppressive activity, releasing tumor necrosis factor-alpha (TNF-α), histamine, and interleukin-10 (IL-10) and suppressing T cells and natural killer (NK) that in turn induce immune tolerance mediated by regulatory T cells (Treg)." (PMID 35140718, 2022). "Furthermore, cytokines such as GM‐CSF, macrophage colony‐stimulating factor (M‐CSF), IL‐6, IL‐10, IL‐1β, PGE2, and TGF‐β, whether secreted or produced by tumor‐derived exosomal vesicles, enter the bone marrow or circulation, and generate MDSCs." (PMID 35791509, 2022). "Elevated IL-10 levels could be explained by the increased number of Treg cells found in the TME in treated tumors and might represent some of the immunosuppressive mechanisms utilized by tumor cells to combat vaccination." (PMID 35651802, 2022). "The drug initially promotes proliferation and cytotoxicity of tumour-infiltrating cytotoxic T cells after one cycle of treatment, but after repeated cycles, the anti-tumour immune functions get impaired, with the release of immune-suppressive factors such as TGF-ß and IL-10." (PMID 35742825, 2022). "Autophagosome-derived exosomes obtained from malignant effusions of cancer patients could activate the differentiation of human B cells into IL-10-producing B cells with immunomodulatory activities, with the level positively correlating with HMGB1 expression on tumor cell-released autophagosomes." (PMID 36233088, 2022). "In the tumor microenvironment, the constitutive STAT3 activation could be prolonged by STAT3-mediated factors, including vascular endothelial growth factor (VEGF) and interleukin-10 (IL-10), which generate immunosuppression in innate and adaptive immunity." (PMID 35936759, 2022). "In contrast, we did not observe tumor formation in any SCID mouse with MSC or IL10-MSC injection." (PMID 35300585, 2022). "Therefore, the introduction of IL10 gene into MSCs did not remarkably activate tumor-related genes, and it is considered safe for clinical use." (PMID 35300585, 2022). "Awaji found that KRAS mutation could promote the secretion of paracrine factors such as IL4, IL10, and IL13 in tumor cells and simultaneously activate CXCR2 signaling in CAFs, resulting in the formation of a secreted CAF phenotype by activating NF-κB signaling and promoting tumor progression." (PMID 36076911, 2022). "TAM secretes very little IL-12 after polarizing to M2, instead of producing IL-10 and TGF-, which decreases TAM’s antigen-presenting ability, inhibits T cell proliferation and killing ability, and promotes Treg and Th2 recruitment, all intending to assist tumor immune escape." (PMID 36276963, 2022). "Therefore, the contradiction between the higher eNK-cell density and more malignant tumor behaviors might result from the increase in tolerant NK cells in patients with low HDL-C, which were induced by their elevated IL-10 levels." (PMID 36585674, 2022).